SNORD110 (small nucleolar RNA, C/D box 110)
Synonyms: HBII-55
Gene: Small nucleolar RNA gene on chromosome 20 (2,654,212 to 2,654,286, forward strand). Ensembl gene ENSG00000221116.
Gene Ontology:
Biological process: RNA processing
Cellular component: nucleolus
Homologues: Orthologues: macaque SNORD110 (99% identical), guinea pig SNORD110 (89% identical), pig SNORD110 (84% identical), rabbit SNORD110 (84% identical), rat Snord110 (83% identical), mouse Snord110 (80% identical).
Diseases named in the same sentence as SNORD110 in open-access papers:
SNORD110 is named in the same sentence as 1 disease in open-access papers, as found by Europe PMC text mining. Sharing a sentence is not in itself a finding about the gene and the disease.
SNORD110 shares sentences with these, for which no sentence is quoted: leukemia (1 paper).